CPA1 (carboxypeptidase A1)
Description:
Carboxypeptidase that catalyzes the release of a C-terminal amino acid, but has little or no action with -Asp, -Glu, -Arg, -Lys or -Pro. Catalyzes the conversion of leukotriene C4 to leukotriene F4 via the hydrolysis of an amide bond (By similarity).
Synonyms: CPA
Tractability: Small molecule: a structure with a bound ligand is known; a high-quality ligand is known; it belongs to a druggable protein family. Antibody: UniProt places it where antibodies can reach, with medium confidence; UniProt predicts a signal peptide or a membrane-spanning region; its Gene Ontology location is reachable by antibodies, with medium confidence. PROTAC: a small molecule that binds it is known.
Target class: Metallo protease; Metallo protease MC clan; Protease; Metallo protease M14A subfamily; Enzyme
Gene: Protein-coding gene on chromosome 7 (130,380,339 to 130,388,114, forward strand). Ensembl gene ENSG00000091704.
Subcellular location: Secreted
Pathways (Reactome):
Developmental Biology: Developmental Lineage of Pancreatic Acinar Cells
Gene Ontology:
Molecular function: metallocarboxypeptidase activity; protein binding; exopeptidase activity; zinc ion binding
Biological process: leukotriene metabolic process; proteolysis; protein catabolic process; response to cadmium ion
Cellular component: extracellular region
Genetic constraint (gnomAD): Loss-of-function variants: 42 observed, 47.63 expected, observed/expected ratio (o/e) 0.88, 90% interval 0.69 to 1.14. The upper end of that interval is the gene's LOEUF score, 1.14, which puts it in group 4 of 6, group 1 being the genes least tolerant of losing a copy. Missense variants: 458 observed, 544.86 expected, observed/expected ratio (o/e) 0.84, 90% interval 0.78 to 0.91. Synonymous variants: 193 observed, 216.59 expected, observed/expected ratio (o/e) 0.89, 90% interval 0.79 to 1.
Homologues: Orthologues: chimpanzee CPA1 (99% identical), macaque CPA1 (96% identical), pig CPA1 (86% identical), rabbit CPA1 (86% identical), guinea pig CPA1 (84% identical), rat Cpa1 (84% identical), mouse Cpa1 (82% identical), dog CPA1 (71% identical), tropical clawed frog cpa1 (66% identical), zebrafish cpa5 (64% identical), zebrafish cpa1 (62% identical), Caenorhabditis elegans T06A4.1 (38% identical), and 20 more. Paralogues in human: CPA2 (62% identical), CPA5 (61% identical), CPA4 (54% identical), CPB1 (42% identical), CPA6 (38% identical), CPA3 (37% identical), CPB2 (37% identical), CPO (30% identical).